GZMB (granzyme B)
Diseases named in the same sentence as GZMB in open-access papers (continued):
Sharing a sentence is not in itself a finding about the gene and the disease.
colorectal cancer (continued). "In the anti-PD-1-sensitive CT26 murine colorectal carcinoma cell line model, granzyme B expression was upregulated 10 days after treatment and was predictive of the response." (PMID 34832863, 2021). "GZMB contributes to the invasive and metastatic phenotypes in colorectal cancer and urothelial carcinoma." (PMID 33042828, 2020). "Inhibiting GZMB-mediated invasion was successfully accomplished in urothelial and colorectal carcinoma cells by docosahexaenoic acid (DHA) in vitro." (PMID 32764784, 2020). "We previously identified CXCL9-11, together with GZMB (Granzyme B), a key product of cytotoxic T-lymphocytes, as part of a prognostic gene expression signature in colorectal cancer." (PMID 29163806, 2017). "Similarly, it has been demonstrated that colorectal cancer (CRC) cells express GZMB, promoting tumor invasiveness via the epithelial-mesenchymal transition (EMT) pathway." (PMID 41567188, 2025). "LINC02474 inhibits apoptosis by impeding GZMB expression in colorectal cancer." (PMID 38685095, 2024). "LINC02474 by inhibiting GZMB expression to regulate progression of colorectal cancer." (PMID 36366731, 2023). "The down-regulation of LINC02474 promoted the expression of GZMB, and the interference of GZMB could increase the metastatic abilities of colorectal cancer cells while reducing apoptosis." (PMID 37770840, 2023). "A lower level of GZMB is associated with shorter relapse-free survival of TNBC patients, whereas a higher level of GZMB is associated with improved cancer-specific survival of colorectal cancer patients." (PMID 33042828, 2020). "To provide evidence supporting the association of IFN-γ signaling, CD8+ T cell function and the progression of colorectal cancer, we evaluated the protein levels of granzyme B in tissue arrays of colon cancer tissues from human patients with different clinical stages of carcinoma (stages I-V)." (PMID 27935860, 2017). "Furthermore, we investigated gene expression changes in IL8, GZMB and CA2, which have been reported to be associated with colorectal cancer progression, at all time-points in the 15 tumor cases." (PMID 24573535, 2014). "Although the link between GZMB and EMT has been preliminarily validated in colorectal cancer models, further research is necessary to determine its applicability to other tumor types and to clarify its specific role in the EMT process in human tumors." (PMID 41567188, 2025). "In the human colorectal cancer (CRC) cohort, SIN3B expression levels were significantly negatively correlated with CXCL9/10/11 as well as CD8A, GzmA, and GzmB." (PMID 39316363, 2024). "We showed that upon coculture with colorectal cancer cells, peripheral and intestinal iNKT cells expressed TRAIL, Fas ligand, and released granzyme B and perforin." (PMID 34535957, 2021). "The median OS, 3-year and 5-year survival rates of colorectal cancer patients in a high density group of CD8+ T cells, CD4+ T cells, or CD4+ GzmB+ T cells were higher than the low-density group respectively." (PMID 34631551, 2021). "Colorectal cancer surgical patients showed increased NK cell lipid content, higher CD36 expression, decreased granzyme B and perforin production in addition to reduced cytotoxicity in the postoperative period." (PMID 31429730, 2019). "The CAR-NK-92 cells can specifically recognize EpCAM-positive colorectal cancer cells and release cytokines, including IFN-γ, perforin, and granzyme B, and show specific cytotoxicity in vitro." (PMID 30410941, 2018). "Studies have shown that GZMB is a potential prognostic marker for colorectal cancer and is involved in the progression of liver cancer." (PMID 40860340, 2025). "Notably, genes such as DKK1, GZMB, THBS1, and CCL5—recognized for their key contributions to colorectal cancer prognosis—have been incorporated into several existing prognostic models." (PMID 40670378, 2025).
colorectal cancer (continued). "Therefore, NACT enhanced the antitumor immune response by promoting the recruitment of CD4+GzmB+ T cells and CD8+ T cells in colorectal cancer." (PMID 36439457, 2022). "Nevertheless, at least in colorectal cancer, the positive protective value of IL-8 and granzyme B levels in the TME is related to T-cells rather than NK-cells." (PMID 33265951, 2020). "To ensure that the expression of perforin and GzmB was not model-dependent, we next generated MDSCs that closely resemble those found within colorectal carcinoma." (PMID 31212684, 2019). "It has been demonstrated that the increased expression of genes specific for cytotoxic T lymphocytes, as CD8α, granzyme B, or perforin was related to the absence of early metastatic invasion of colorectal cancer, and it could also improve patient survival." (PMID 23349906, 2013). "Two-hundred-fifteen colorectal cancer cases, previously analyzed for microsatellite instability (MSI), were selected for immunohistochemical detection of CD3+, CD8+ infiltration and the expression of granzyme B. Prognostic relevance was assessed by survival analysis." (PMID 20385003, 2010). "Anti-DKK2 treatment induced significant increases in GZMB and CD69 over control IgG treatment in the DKK2high, but not DKK2low sample group, suggesting that DKK2 blockade activates infiltrating CD8+ T cells in human colorectal cancers that express high levels of DKK2." (PMID 32559853, 2020).
colon carcinoma (49 papers, 2014 to 2025). "Granzyme B-specific PET imaging was closely associated with granzyme B expression in CT26 colon tumors." (PMID 30506221, 2019). "We analyzed the expression of the effector molecules of cytotoxic CD8+ T lymphocytes (CTLs) Granzyme B (GZMB), and Perforin (PRF1) encoding genes in the two subtypes of colon cancer." (PMID 38999959, 2024). "In colon tumors, GZMB has been shown to be highly expressed in the proximal colon and is characterized by MSI-high and BRAF mutations, with higher levels of GZMB being associated with longer OS and CSS." (PMID 35846123, 2022). "In the current study, we have assessed the ability of [18F]AlF-mNOTA-GZP, a peptide probe targeting granzyme B to serve as a PET imaging biomarker of combined ICI/chemotherapy in a syngeneic mouse model of colon cancer." (PMID 33713000, 2021). "Here, we showed that human intestinal and peripheral blood‐derived iNKT cells exerted killing activities against colon cancer cells through different mechanisms, including granzyme B and perforin release and death receptor pathways." (PMID 34535957, 2021). "As it occurred with TRAIL and Fas ligand, frequencies of GZMB+ cells changed after incubation with colon cancer cells." (PMID 34535957, 2021). "Tim-3 signaling decreased the expression of perforin and granzyme B in T cells, which reduced the cytotoxicity of T cells against colon cancer cells." (PMID 34434188, 2021). "Lenvatinib treatment decreased the number of CD31+ tumor blood vessels, diminished the amount of CD11b+F4/80+ TAMs and increased the percentage of activated CD8+ T cells secreting interferon (IFN)-γ+ and granzyme B (GzmB) in CT26 colon cancer mouse model." (PMID 34209679, 2021). "As same as in human colon cancer tissue, 5F8 treatment significantly increased the expression of Granzyme B (GZMB) in CD8+ T cells, as well as in NK cells." (PMID 32559853, 2020). "The subsets of TIL, the ratio of CD3+, CD8+, and granular enzyme B(GZMB) + T cells are regarded as predictive parameters in colon cancer." (PMID 32646394, 2020). "In line with the downregulation of GZMB in colon tumors from AAs, we also observed an upregulation of exhausted CD8+, T regulatory and myeloid cells in this cohort when compared to CAs." (PMID 32983990, 2020). "Our findings indicate that IFN-I intrinsic signaling in T cells is also essential for expression of granzyme B and T cell function in colon carcinoma growth control in vivo." (PMID 31228946, 2019). "The involvement of GZMB produced by neutrophils in the anti-tumor effect of lipid A has also been demonstrated in a mouse model of colon cancer." (PMID 29983866, 2018). "Taken together, these results indicate that animal but also human colon tumors are infiltrate by neutrophils which are characterized by the expression of the GZMB." (PMID 29983866, 2018). "One of the most important aspects of this study is that a large proportion of TAN expressed GZMB and was localized into colon tumors from rats, mice and from patients." (PMID 29983866, 2018). "Here we have identified a subpopulation of colon tumor-infiltrating neutrophils, in rat and mouse models but also in human, which expressed GZMB." (PMID 29983866, 2018). "We noted that colon tumor cells expressing the physiologically inhibitor of GZMB, the serpin B9, grew more slowly in mice as compared to wild type cells (80% reduction in tumor volume)." (PMID 29983866, 2018). "We previously identified chemokines CXCL9, CXCL10, and CXCL11, as well as GZMB (Granzyme B), as part of a prognostic gene signature in colon cancer." (PMID 29163806, 2017). "Likewise, αPD-1 induced accumulation of mature (CD62L–) and cytotoxic (CD69+GZMB+) NK cells in the MC38 colon cancer model." (PMID 40530504, 2025). "Also, in animal models of cancers including MC38 colon cancer, intratumoral granzyme B quantification by PET imaging was a highly sensitive and specific early measure of therapeutic efficacy for checkpoint inhibitor regimens." (PMID 35514996, 2022).
colon carcinoma (continued). "Additionally, B7-H5 blockade using a B7-H5 monoclonal antibody (B7-H5 mAb) effectively suppressed the growth of MC38 colon cancer tumors by enhancing the infiltration and Granzyme B production of CD8+ T cells." (PMID 34537815, 2021). "Moreover, TIM-3 signaling significantly inhibited the killing efficiency of Vδ2 T cells against colon cancer cells and reduced the secretion of perforin and granzyme B." (PMID 34820398, 2021). "In summary, the current study shows that in vivo molecular imaging of intra-tumoural granzyme B using [18F]AlF-mNOTA-GZP is able to stratify tumour response to a range of ICIs administered to preclinical colon cancer models given as monotherapies or in combination." (PMID 32705455, 2020). "Lastly, we showed a correlation between our gene expression findings and the ones available from TCGA that demonstrated that Granzyme B could be a therapeutic target for AA colon cancer patients." (PMID 32983990, 2020). "We could not observe the expression of perforin compared to the isotype control with the used antibody; however, we observed that both MDSC-subsets expressed high levels of GzmB in both colon cancer patients and healthy donors." (PMID 31212684, 2019). "We moreover showed that MDSCs isolated from peripheral blood of colon cancer patients express GzmB." (PMID 31212684, 2019). "In a rat and mouse models, we show that a substantial amount of colon tumor associated-neutrophils (TAN) expressed the cytolytic enzyme granzyme B, which is absent in spleen or blood circulating neutrophils." (PMID 29983866, 2018). "Indeed, in a cohort of 72 colon cancer cell lines, GZMB was primarily expressed in CMS2 cell lines." (PMID 34972191, 2021). "Previous research showed in tumor-infiltrating cytotoxic T lymphocytes (CTLs) in human colon carcinoma that SUV39H1 mediated H3K9me3 marks at the promoters of CTL effector genes (e.g., GZMB, PRF1, FASLG, and IFNG)." (PMID 40059829, 2025). "In this study, the average expressions of CD8A, CD8B, GZMA, GZMB, and PRF1 genes were used to represent level of CTL in colon cancers." (PMID 38327746, 2024). "There is data suggesting that adoptive chimeric antigen-receptor-modified NK-cells transfected with EpCAM gene selectively targets EpCAM-expressing colon cancer cells with a release of interferon (IFN)-γ, perforin and granzyme-B and specific cytotoxicity." (PMID 37533952, 2023). "CYP19A1 knockdown boosted tumor-infiltrating CD8+ T cells and enhanced GzmB and IFNγ production, indicative of CD8+ T cells-elicited adaptive immunity against colon cancer, which were amplyfied in combination therapy." (PMID 37055842, 2023). "The activated γδT cells release perforin and granzyme B to secrete cytokines IFN-γ, TNF-α, as well as TRAIL, Fas/FasL and many other ways to exert an effect on colon cancer cells." (PMID 36685942, 2022). "Expression levels of LGR5, VSIG4, GZMB, and ITLN1 were tested in colon cancer and adjacent normal tissues via qRT-PCR method." (PMID 36186438, 2022). "The data from the cohort of 72 colon cancer cell lines, confirmed that GZMB is primarily expressed in CMS2 cell lines and that GZMB expression there is rather a tumor-intrinsic property." (PMID 34972191, 2021). "We have assessed the ability of a fluorine-labelled peptide, [18F]AlF-mNOTA-GZP, targeting granzyme B, to stratify ICI response in two syngeneic models of colon cancer, CT26 and MC38." (PMID 32705455, 2020). "To assess the value of these findings, we next analyzed the expression of perforin and GzmB in M-MDSCs (CD11b+CD33+CD14+HLA-DRlow) and PMN-MDSCs (CD11b+CD33+CD15+) of colon cancer patients and healthy donors." (PMID 31212684, 2019). "In a study in colon cancer, the densities of CD3+, CD8+, granulysin, and granzyme B (GZMB)+, and CD45RO+ cells in each tumor region (tumor center and invasive margin) were shown to be prognostic." (PMID 29385739, 2018).
colon carcinoma (continued). "Of these, six mRNA including ECM1, GZMB, KLK10, CCL20, MMP9, and IL7 have been previously reported to have a prognostic role in colon cancer." (PMID 29377588, 2018). "Granzyme B is a pro-apoptotic cytotoxin produced and secreted by immune and non-immune cells but also by neoplastic cells, e.g., cancer of the colon." (PMID 37532996, 2023). "Incubation of CL40 colon cancer cells with IMC-KRASG12D together with HLA-A*11+ PBMC resulted in IMC-KRASG12D concentration dependent IFNγ, IL-2 and Granzyme B release as well as redirected T cell killing in a time- and dose-dependent manner with a mean EC50 value of 28.5 ± 25 pM." (PMID 36088370, 2022). "A combination of oral AHCC® and dual immune checkpoint blockade (DICB), including PD-1/CTLA-4 blockade, had reduced tumor growth and increased granzyme B and Ki-67 expression by tumor-infiltrating CD8+ T cells in MC38 colon cancer bearing mice compared to a combination of water and DICB." (PMID 35514996, 2022). "Even if the presence of functional perforin and granzyme B is fundamental for iNKT cell killing of CRC cells, some iNKT lines expressed TRAIL on their membranes, and some of them upregulated Fas ligand upon encounter with colon cancer cells." (PMID 34535957, 2021). "Our data showed that compared to the control group, SuperPDL1exo could enhance infiltration of CD8+ T cells in tumors; increase the expression of cytotoxic granules such as perforin, granzyme B, and granzyme A; and exert antitumor effects in the MC38 colon cancer model." (PMID 37529049, 2023). "We investigated the use of a granzyme B targeted peptide (GZP) as a cancer theranostic agent, radiolabeled with 68Ga (68Ga-GZP) as a PET imaging agent and radiolabeled with 90Y (90Y-GZP) as a targeted radionuclide therapy agent for combinational therapy with ICI in murine models of colon cancer." (PMID 35890355, 2022). "Similarly, in the colon cancer model, the combination of vistusertib, an mTOR inhibitor, and anti-CTLA-4, an immune checkpoint blockade, increased the cytotoxic activity of intratumoral CD8+ T cells, by the production of molecules such as IFN-γ and granzyme B." (PMID 36077620, 2022). "Transcriptome analysis of 57 advanced colon cancer samples revealed that one of the non-T cell inflamed subtypes (group 4) had low expression of CD8a, IFNG and GZMB with high expression of SCD1 and CTNNB1(β-catenin) and its downstream molecules including VEGFA and TCF12." (PMID 35793868, 2022).
lung carcinoma (45 papers, 2003 to 2026). "Research has demonstrated that the release of soluble substances by lung cancer cells can hinder the production of granzyme B, perforin, and IFN‐γ, and this interference is associated with the PGE2/COX2 pathway." (PMID 39588940, 2024). "Recently, we reported that the number of granzyme B-expressing NK cells increases in the early stages of lung cancer." (PMID 38361934, 2024). "We observed a notable granzyme B-expressing NK cell response in most lung cancer patients undergoing autologous DC/Gal therapy." (PMID 38361934, 2024). "MB-PDT also potentiated CD8+ T cell-mediated cytolysis of lung cancer via granzyme B in lung cancer cells and primary human lung cancer organoids." (PMID 36077656, 2022). "In this study, we report that methylene blue photodynamic therapy decreases the proliferation of lung cancer cells and patient derived non-small cell lung cancer organoids via immunogenic cells death and granzyme B mediated cytolysis." (PMID 36077656, 2022). "We have previously demonstrated that healthy CD8+ T cells expressed highly granzyme B in co-cultured with lung cancer HCC827 and A549 cells in vitro." (PMID 34680466, 2021). "In lung cancer, we found that perforin, granzyme B, IFN-γ, and CD107a were lower in PD-1+ NK cells than those in PD-1- NK cells." (PMID 32788875, 2020). "It was also reported that significantly decreased expression of perforin, granzyme B, and IFN-γ in T, NKT-like, and NK cells is associated with lung cancer tissues compared with normal lung tissues from patients." (PMID 31275318, 2019). "Aminoflavone 8 enhanced NK-92MI cell cytotoxicity, as evidenced by the elevated expression of cytotoxic effectors, such as IFN-γ, perforin, and granzyme B. Aminoflavone 8 also inhibited STAT3 phosphorylation in A549 lung cancer and NK-92MI cells under co-culture conditions." (PMID 41688864, 2026). "Additionally, the effects of immunotoxins and their components, as a control, namely, scFv of Rova, Granzyme B, and Typhoid Toxin, were evaluated individually over 24 h on the A549 lung cancer cell line." (PMID 40177519, 2025). "Moreover, lung cancer-derived EVs are enriched with circUSP7 to attenuate granzyme B and perforin secretion by CD8 + T cells, thereby facilitating lung cancer resistance to anti-PD-1 immunotherapy." (PMID 40908470, 2025). "Additionally, the release of granzyme B by blood‐derived NK cells in lung cancer patients is diminished when compared to that of normal tissue." (PMID 39588940, 2024). "Based on this hypothesis, we measured the serum concentrations of perforin, granzyme B, and other immune modulators as biomarkers of the response to PD‐1 blockade in non‐small cell lung cancer (NSCLC) patients." (PMID 32915511, 2020). "In lung cancer, CD28−PD1+ and CD28−PD1− T cells displayed enhanced secretory capabilities for granzyme B, IFN-γ, and TNF-α, whereas CD28+PD1− and CD28+PD1+ T cells exhibited diminished secretory functions, consistent with our findings." (PMID 40136325, 2025). "Decreased levels of granzyme B in NK cell and CD8+ T cells are also observed in lung cancer where higher levels of granzyme B after immunotherapy furthermore correlate with better clinical outcome." (PMID 37691935, 2023). "Granzyme B was considered a hydrolase enzyme leading to tumor cell apoptosis but IFNγ induced STAT3-mediated PD-L1 and MCL1 expression in EGFR-positive lung cancer cells." (PMID 34685495, 2021). "The CD8+ T cell and the functional markers IFN-γ, Granzyme B, and Perforin were lower in lung cancer tumor sites compared to adjacent normal tissues [CD8 P < 0.0001, IFN-γ P < 0.0001, Granzyme B P < 0.0001, Perforin P < 0.0001]." (PMID 30744691, 2019).